TYK2 (tyrosine kinase 2)
Diseases named in the same sentence as TYK2 in open-access papers (continued):
Sharing a sentence is not in itself a finding about the gene and the disease.
tuberculosis (16 papers, 2018 to 2026). A chronic, recurrent infection caused by the bacterium Mycobacterium tuberculosis. "In fact, the TYK2:p.Pro1104Ala variant is the main common risk factor for tuberculosis in endemic regions and increases the risk of severe COVID‐19." (PMID 39835539, 2025). "Carriers of the TYK2:p.Pro1104Ala variant are predisposed to tuberculosis, acting possibly through reduced IL23 and IL12 signalling‐dependent IFN‐gamma production." (PMID 39835539, 2025). "The same is true for rare inborn errors underlying tuberculosis in humans, including complete IL-12Rβ1 deficiency, certain TYK2 deficiencies, interleukin-2 inducible T cell kinase (ITK) deficiency, and PD1 deficiency." (PMID 37047709, 2023). "Of note, the common TYK2 P1104A missense variant underlies tuberculosis in approximately 1% of patients with European ancestry and is associated with an impaired IL-23-dependent IFN-γ immunity." (PMID 37047709, 2023). "Similar to TYK2 deficient patients, individuals homozygous for the TYK2 1104A variant have an increased frequency of tuberculosis." (PMID 30888520, 2019). "The influence of TYK2 genetic variants have been previously assessed in other infectious diseases, such as tuberculosis and in the human immunodeficiency virus (HIV)." (PMID 29304122, 2018). "Moreover, the common homozygous TYK2 P1104A mutation (~1 out of 600 of Europeans) increases the risk of tuberculosis upon exposure to Mycobacteriumtuberculosis." (PMID 36377664, 2022). "For example, rare variants leading to complete TYK2 deficiency result in monogenic susceptibility to Mycobacterium tuberculosis (TB) and Mendelian suspetibility to mycobacterial disease (MSMD) with relatively high penetrance (∼80%)." (PMID 41608500, 2025). "This hypothesis is in line with recent findings, where homozygosity for TYK2 P1104A confers a predisposition for tuberculosis by a preferential impairment of IL-23-dependent IFN-γ immunity, which could explain the protective effect to SLE, observed in this study." (PMID 31434951, 2019). "Additionally, the TYK2:p.Pro1104Ala variant selectively impairs cellular responses to IL23, but not to IFN‐alpha or IL10, in agreement with its predisposing effect for tuberculosis." (PMID 39835539, 2025). "Exome sequencing data also allowed the identification of a missense tyrosine kinase 2 (TYK2) gene variant, P1104A, which selectively disrupts the induction of interferon-γ by interleukin-23 and is a common monogenic etiology of tuberculosis in non-European countries where TB is endemic." (PMID 35401413, 2022). "In addition to conventional anti-tuberculosis treatment, injection of recombinant IFN-γ and transduction of the TYK2 gene are new treatment options." (PMID 35096640, 2021).
ulcerative colitis (15 papers, 2017 to 2025). An inflammatory bowel disease involving the mucosal surface of the large intestine and rectum. "TEM imaging showed lower levels of TYK2 in cancer than in ulcerative colitis." (PMID 39518103, 2024). "The TEM results obtained in this study may suggest an important biological role of TYK2 in the mechanism towards colorectal adenocarcinoma carcinogenesis, since ulcerative colitis is often a pre-cancerous state for this cancer." (PMID 39518103, 2024). "TYK2 inhibitors improved certain clinical measures of ulcerative colitis severity, like improved modified Mayo endoscopic and Mayo rectal bleeding sub-score in the intervention group; however, there was no strong evidence of effect on clinical remission." (PMID 36842216, 2023). "For that purpose, fresh tissue biopsies collected during colonoscopy from patients with ulcerative colitis and CRC were used to assess the level of TYK2 and its distribution in cells using electron microscopy." (PMID 39518103, 2024). "Independently assessed TYK2 immunoreactivity in fresh colonic biopsies from CRC and ulcerative colitis (UC) patients showed that the kinase distribution was greater in UC than in cancer." (PMID 39518103, 2024).
psoriatic arthritis (14 papers, 2021 to 2026). Joint inflammation associated with psoriasis. "In addition, an empirically annotated TYK2 pathway will also allow better targeting of other dermatological and autoimmune conditions, such as psoriatic arthritis and inflammatory dermatitis, as shown in this study, both of which may be best treated with such a therapy." (PMID 39684939, 2024). "The TYK2 inhibitor deucravacitinib has shown efficacy in treatment of psoriatic arthritis 40, but no trials have yet been reported in axial spondyloarthritis." (PMID 40709250, 2025).
leukemia (11 papers, 2012 to 2023). A malignant (clonal) hematologic disorder, involving hematopoietic stem cells and characterized by the presence of primitive or atypical myeloid or lymphoid cells in the bone marrow and the blood. "Past TYK2 pseudokinase and kinase domain modeling of the closed state similarly showed the majority of reported leukemia mutations face the JH1-JH2 interface." (PMID 37834019, 2023). "Although TYK2 is more rarely affected by somatic point mutations, growing evidence suggests that germline mutations in TYK2 can drive leukemia." (PMID 33672930, 2021). "Disease-driving mutations in TYK2 are rarely found in leukemia when compared to other JAK family members." (PMID 33672930, 2021). "TYK2 GOF point mutations occur less frequently in leukemia, although many single nucleotide polymorphisms (SNPs) in the coding region of the TYK2 gene have been described, with over 100 nonsynonymous mutations associated with a number of diseases." (PMID 34439323, 2021). "The susceptibility to infection is a hallmark of leukaemia, and it is associated with TYK2 deficiency in humans and mice." (PMID 33260630, 2020). "In addition to the somatic cancer cell mutations, two GOF TYK2 germline mutations (P760L and G761V) were found in pediatric patients developing several de novo leukemias." (PMID 31694222, 2019). "Different types of leukemia harbor genomic aberrations in all four JAKs (JAK1, JAK2, JAK3, and TYK2), most of which are activating somatic mutations and less frequently translocations resulting in constitutively active JAK fusion proteins." (PMID 33672930, 2021). "It is only recently, that mutations in TYK2, a JAK kinase family member, were found in the germline of patients presenting with a second primary leukemia, causing constitutive JAK signaling and a propensity for developing leukemia." (PMID 30443258, 2018). "As TYK2 JH1 inhibitors have shown activity in T-ALL, TYK2 JH2 inhibitors might have utility also in the treatment of leukemia." (PMID 33672930, 2021). "In pediatric ALL patients, whole exome sequencing identified TYK2 mutations in the JH2 pseudokinase domain (G761V and P760L) that promote TYK2 autophosphorylation, activate STAT1/3/5, and are suggested to contribute to the development of leukemia." (PMID 34439323, 2021). "In addition, indirect evidence supports the role of TYK2 signaling in leukemogenesis; inactivation of TYK2 in mice was shown to lead to the development of leukemia and lymphoma, plausibly resulting from the impaired immune defense against tumor cells." (PMID 33672930, 2021). "The first leukemia patients carrying TYK2 fusion genes described were combinations of the TYK2 kinase domain and a part of the pseudokinase domain with 5′ portions of nucleophosmin (NPM) 1, polyadenylate binding protein (PABPC) 4, or the transcription factors MYB or NFκB2." (PMID 31694222, 2019). "In addition to leukemia-driving mutations, we have identified recurrent pathogenic mutations CRLF2 p.F232C (n = 7), TYK2 p.A413T (n = 7), JAK2 p.R683G (n = 4), KRAS p.G12D (n = 4), FLT3 p.Y842C (n = 3) and PTPN11 p.D61V (n = 3), previously frequently found in pediatric ALL." (PMID 34830809, 2021).
prostate carcinoma (11 papers, 2015 to 2024). A carcinoma that arises from epithelial cells of the prostate gland. "A recent Mendelian randomization (MR) study observed positive associations of a TYK2 loss-of-function mutation that mimic TYK2 inhibition with increased risk of lung cancer, non-Hodgkin lymphoma, and possibly prostate cancer." (PMID 36842216, 2023). "The observed association for prostate cancer is in agreement with a recent MR study where TYK2 inhibition mimicked by a loss-of-function variant in TYK2 (rs34536443) showed associations with lung cancer, non-Hodgkin lymphoma, and advanced prostate cancer." (PMID 36842216, 2023). "TYK2 signaling has also been implicated in tumor-cell infiltration and metastasis in human prostate cancer patients, a finding recapitulated in Eμ-Myc transgenic mice, in which TYK2 deficiency reduces tumor-cell invasiveness into the liver." (PMID 31936322, 2020). "In prostate cancer, TYK2 influences the invasiveness of prostate cancer cells, While, in osteosarcoma cell lines, TYK2 is essential for cancer cell survival." (PMID 33731185, 2021). "Early proteomic analyses first reported the role of TYK2 as a biomarker in breast, cervical, colorectal and prostate cancers." (PMID 34439323, 2021). "Similarly, in prostate cancer cells, inhibition of TYK2 gene expression by shRNA decreases invasion through decreased urokinase-type plasminogen activator (uPA), which is involved in the activation of MMPs that degrade extracellular matrix proteins." (PMID 34439323, 2021). "In colon cancer, GRPR enhances invasion through the RhoA/ROCK pathway, while in prostate cancer, GRPR overexpression promotes a malignant phenotype via activation of AKT1, PKCε, TYK2, and MST1 pathways." (PMID 39768218, 2024). "PTP1B (also known as PTPN1) is a protein tyrosine phosphatase, whose expression is amplified by androgens in prostate cancer cells and which dephosphorylates IGFR, Jak2, and Tyk2, kinases crucial to cytokine signaling pathways." (PMID 31118931, 2019). "Taken together, these data support the hypothesis that targeting TYK2 and/or MST1 with specific inhibitors could be a useful approach in the blockage of prostate cancer progression in ETV1- positive PCa." (PMID 26097883, 2015).
lymphoma (10 papers, 2012 to 2025). A malignant (clonal) proliferation of B- lymphocytes or T- lymphocytes which involves the lymph nodes, bone marrow and/or extranodal sites. "Correspondingly, loss of Tyk2 in an NPM-ALK lymphoma mouse model delayed tumor growth and prolonged overall survival." (PMID 34439323, 2021). "T-cell-specific loss of TYK2 in a transgenic mouse model of NPM-ALK driven lymphoma resulted in delayed tumor growth and significantly prolonged overall survival of the mice." (PMID 30131584, 2019). "Genetic studies in a transgenic NPM-ALK driven lymphoma model also demonstrate that T cell-specific loss of Tyk2 delays the onset of tumors and prolongs the survival of mice." (PMID 30131584, 2019). "Finally, it has been reported that TYK2 deficiency in mice increases the susceptibility to develop Abelson-induced B lymphoid leukaemia/lymphoma linked to a diminished cytotoxic capacity of Natural Killer (NK) and NKT cells as a consequence of decreased IFN-γ production." (PMID 33260630, 2020). "The role of TYK2 in lymphoma development and progression is not yet fully understood, although, the presence of activating TYK2 fusion proteins in a small subset of ALCL patients indicates its importance." (PMID 30131584, 2019). "Additionally, future preclinical studies focused on inhibition of the TYK2 fusion partner must also be considered in the development of treatment for these fusion-driven lymphomas." (PMID 35042970, 2022). "As in the mouse model, we found that expression levels of MCL1 were profoundly downregulated by TYK2 depletion, suggesting that TYK2’s ability to promote lymphoma cell survival may be mediated through MCL1." (PMID 30131584, 2019). "Loss of Tyk2 did not affect Bcl2 expression levels in these lymphoma cells." (PMID 30131584, 2019). "TYK2 fusions such as MYB::TYK2, NPM1::TYK2, NFkB2::TYK2, and PABPC4::TYK2 are found in lymphomas and ALL leading to constitutive TYK2 signaling and contributing to malignant transformation." (PMID 40140631, 2025). "Correspondingly, TYK2 is highly expressed in lymphomas including ALCL, and activated TYK2 leads to increased ALCL cell survival, which is mediated through STAT1/3 and the anti-apoptotic protein MCL-1." (PMID 34439323, 2021). "The importance of TYK2 for NK cell- and CD8+ T cell-targeted tumor growth restriction was confirmed by studies with local tumor transplant models, using lymphoma (RMA-S and RMA-Rae1) and adenocarcinoma (MC38) cells." (PMID 31936322, 2020). "Here we demonstrate that TYK2 is highly expressed in all cases of human ALCL, and that in a mouse model of NPM-ALK-induced lymphoma, genetic disruption of Tyk2 delays the onset of tumors and prolongs survival of the mice." (PMID 30131584, 2019). "To elucidate the role of TYK2 in tumorigenesis, we focused on ALCL as a well-defined lymphoma subtype." (PMID 30131584, 2019). "Related to regulation via Tyk2, another study has reported that expression of SHP-1 is diminished or abolished in most lymphoma cell lines and in some colorectal cancer." (PMID 22218495, 2012). "It is unclear whether recent safety concerns (ie, elevated rates of lung cancer and lymphoma) related to similar medications (ie, other JAK inhibitors) are shared with this novel TYK2 inhibitor." (PMID 35747941, 2022). "Lymphomas in this model lacking Tyk2 have reduced STAT1 and STAT3 phosphorylation and reduced expression of Mcl1, a pro-survival member of the BCL2 family." (PMID 30131584, 2019). "Interestingly, in lymphomas from CD4-NPM-ALKLCKΔΔTyk2 mice, MCL1 expression was decreased at both the mRNA and protein levels as compared to CD4-NPM-ALK mice expressing TYK2 (P < 0.0001)." (PMID 30131584, 2019).
acute lymphoblastic leukemia (9 papers, 2014 to 2025). Leukemia with an acute onset, characterized by the presence of lymphoblasts in the bone marrow and the peripheral blood. "Previous studies have reported TYK2 mutations in hematologic malignancies, particularly in myeloproliferative disorders such as acute lymphoblastic leukemia." (PMID 40519492, 2025). "TYK2 point mutations found in T-ALL (T-cell acute lymphoblastic leukemia) cell lines exhibited transformation potential via the STAT1/BCL2 pathway." (PMID 35042970, 2022). "A subsequent study identified an oncogenic TYK2-STAT1 pathway in T-cell acute lymphoblastic leukemia (T-ALL) cell lines, mediated through gain-of-function TYK2 mutations or activation of IL10 receptor signaling, that leads to the upregulation of BCL2 and T-ALL cell survival." (PMID 26654227, 2015). "T cell acute lymphoblastic leukemia (T-ALL) patients may also benefit from therapies eradicating TYK2 expression." (PMID 24833526, 2014).
lung carcinoma (9 papers, 2014 to 2026). "Analyses show that genetically proxied TYK2 inhibition increases lung cancer and non‐Hodgkin lymphoma risk." (PMID 35747941, 2022). "In addition to the increased infection risk, there is a potential risk of lung cancer, non-Hodgkin lymphoma, and reduced β-cell mass with TYK2 inhibition, indicating that further safety assessments will be needed for long-term treatment with TYK2 inhibitors." (PMID 38351043, 2024). "In the primary analysis, each copy of the minor allele of rs34536443, representing partial TYK2 inhibition, was associated with an increased risk of lung cancer (OR 1.15, 95% CI 1.09‐1.23, P = 2.29 × 10−6) and non‐Hodgkin lymphoma (OR 1.18, 95% CI 1.05‐1.33, P = 5.25 × 10−3)." (PMID 35747941, 2022). "Our analyses using an established partial loss‐of‐function mutation to mimic TYK2 inhibition provide genetic evidence that therapeutic TYK2 inhibition may increase risk of lung cancer and non‐Hodgkin lymphoma." (PMID 35747941, 2022). "Findings from our analysis therefore suggest that therapeutic TYK2 inhibition may increase risk of lung cancer and non‐Hodgkin lymphoma among populations who may already be at elevated risk of these diseases." (PMID 35747941, 2022). "Recent studies show that, in liver and lung carcinoma, high levels of CLDN9/12/17 caused activation of TYK2 and STAT1/3 and promoted metastasis." (PMID 31694222, 2019). "The ambivalent role of STAT1 and STAT3 in lung cancer prompted us to analyze if the TYK2-dependent activation of the reporter is mediated by STAT1 or STAT3." (PMID 24833526, 2014). "Our findings, suggesting potential adverse target‐mediated effects of TYK2 inhibition on lung cancer and non‐Hodgkin lymphoma, could have important implications for future safety assessment of deucravacitinib and other TYK2 inhibitors in development." (PMID 35747941, 2022). "Moreover, we show that SIAH2 reduces TYK2 and the TYK2-dependent activation of STAT3 in lung cancer cells." (PMID 24833526, 2014). "We asked whether TYK2 evokes STAT3 signaling in lung cancer cells and if SIAH2 can attenuate this process." (PMID 24833526, 2014). "In lung cancer, the tight junction protein claudin-12 stimulates EMT via TYK2 and STAT1 through increased cell migration and invasion." (PMID 34439323, 2021). "In lung cancer cells, overexpression of the E3 ubiquitin ligase seven-in-absentia-2 (SIAH2) accelerates the proteasomal degradation of TYK2, thereby attenuating STAT3 signaling." (PMID 31694222, 2019). "Recently, Muller and colleagues have demonstrated how SIAH2 accelerates the proteasomal degradation of TYK2, leading to STAT3 inactivation in lung cancer cells." (PMID 26580787, 2015).
anaplastic large cell lymphoma (8 papers, 2016 to 2021). Anaplastic large cell lymphoma (ALCL) is a rare and aggressive peripheral T-cell non-Hodgkin lymphoma, belonging to the group of CD30-positive lymphoproliferative disorders, which affects lymph nodes and extranodal sites. "TYK2 is a member of the JAK family of tyrosine kinases that is involved in chromosomal translocation-induced fusion proteins found in anaplastic large cell lymphomas (ALCL) that lack rearrangements activating the anaplastic lymphoma kinase (ALK)." (PMID 30131584, 2019). "In line with our findings, it was recently reported that in anaplastic large cell lymphomas (ALCLs) constitutively active Tyk2 fusion proteins are oncogenic by driving the STAT3 signaling pathway." (PMID 29162862, 2017). "We and others have recently demonstrated that a small subset of systemic (<5%) and cutaneous (~20%) Anaplastic Large Cell Lymphomas (ALCL) bears ROS1 or TYK2 fusions." (PMID 26943776, 2016). "Numerous genomic rearrangements were discovered in human anaplastic large cell lymphoma (ACLC) patients with an RNAseq screen, including two fusions of TYK2 to nuclear factor of kappa light polypeptide gene enhancer in B cells 2 (NFκB2) or poly(A) binding protein cytoplasmic 4 (PABPC4)." (PMID 34439323, 2021). "Recently, activation of TYK2 has been noted in a number of malignancies including T-cell acute lymphoblastic leukemia (T-ALL), anaplastic large cell lymphoma (ALCL) and nerve sheath tumor." (PMID 30131584, 2019). "Cresenzo and colleagues performed a whole transcriptome sequencing for anaplastic lymphoma kinase negative anaplastic large cell lymphoma (ALK-ALCL) samples where they recurrently found a NFkB2-TYK2 hybrid transcript in which the coding region of the NFkB2 is fused to TYK2." (PMID 33672930, 2021).